ADM (adrenomedullin)
Diseases named in the same sentence as ADM in open-access papers (continued):
Sharing a sentence is not in itself a finding about the gene and the disease.
tumor (continued). "Moreover, hypoxia-induced adrenomedullin is implicated in various processes including inhibition of apoptosis-mediated cell death, tumor metastasis, angiogenesis, and inhibition of immune surveillance." (PMID 28620317, 2017). "Active tumour growth, hypoxia and the associated overexpression of ADM might be responsible for the increased production and release of the peptide." (PMID 14612905, 2003). "In summary, considering the high expression of ADM in the majority of tumors and its significant association with tumor progression and poor prognosis, therapeutic interventions targeting ADM and its associated signaling pathways have demonstrated substantial anti-tumor efficacy." (PMID 40565016, 2025). "In addition, our study further demonstrated that ADM expression was positively associated with tumor mutational burden (TMB) and microsatellite instability (MSI) in several cancers, including COAD and TET, suggesting ADM’s potential as a biomarker for predicting the efficacy of immunotherapy." (PMID 40529377, 2025). "However, ADM expression was lower in tumor tissues but considered as a prognostic risk gene." (PMID 36117156, 2022). "PC cells secrete tumor-inducing factors, such as adrenomedullin, leading to an increase in insulin resistance and beta cell dysfunction in PCDM." (PMID 40487412, 2025). "Among the most relevant pro-angiogenic factors, such as VEGF and bFGF, induced by tumor hypoxia, we also find adrenomedullin (AM)." (PMID 41226782, 2025). "In particular, ADM staining was localized to the cytoplasm of tumor cells and a subset of tumor-infiltrating immune cells, corroborating its cell-type specificity observed in scRNA-seq." (PMID 40547013, 2025). "These dynamic molecular-level alterations clearly indicate elevated ADM expression strongly correlates with attenuated tumor microenvironment immune responses." (PMID 41450464, 2025). "Collectively, these results show that SPP1hi Mφs and VEGFAhi neutrophils colocalize with APLNhi tip cells to form an angiogenic niche, and that these myeloid subtypes actively engage in modulating the tumor vasculature by expressing ADM and VEGFA." (PMID 41203997, 2025). "For instance, ADM exhibits context-dependent modulation of oncogenic signaling pathways across different tumor types, and its pro-tumorigenic mechanisms remain incompletely characterized." (PMID 40565016, 2025). "HIFs modulate ADM expression through multiple pathways, facilitating the adaptation of tumor cells to hypoxic environments." (PMID 40565016, 2025). "In the preceding discussion, it was elucidated that the role of ADM in facilitating tumor progression is contingent upon multiple signaling pathways." (PMID 40565016, 2025). "The blockade of ADM signaling pathways or its receptors using specific antibodies has been shown to effectively suppress tumor growth and metastasis." (PMID 40565016, 2025). "ADM was identified as a tumour promoter in BTC, exhibiting higher expression compared to normal tissues." (PMID 40074697, 2025). "Meanwhile, hypoxia-activated mesenchymal stromal cells contribute to tumor progression by destabilizing endothelial junctions through the secretion of adrenomedullin, leading to the formation of hyperpermeable vasculature." (PMID 40800581, 2025). "Clinically, ADM was highly expressed in tumor tissues and shows elevated concentrations in the peripheral blood of patients with advanced-stage LUAD." (PMID 40547013, 2025). "Tumor-secreted mediators, such as adrenomedullin, and tumor-derived exosomes enriched in proteins and microRNAs can impair β-cell function and lead to peripheral insulin resistance." (PMID 41597354, 2025). "Exhaustion markers including PDCD1, IDO1, and HAVCR2 were predominantly enriched in tumor-adjacent regions, which exhibited partial spatial overlap with ADM expression." (PMID 40547013, 2025).
tumor (continued). "Consistent with transcriptomic data, ADM protein expression was markedly elevated in LUAD tumor tissues compared to normal lung parenchyma and adjacent non-tumorous tissues." (PMID 40547013, 2025). "In the majority of tumors, ADM expression is elevated compared to that in healthy tissues, exhibiting properties that promote tumor cell proliferation and inhibit apoptosis." (PMID 40565016, 2025). "The results showed that the expression level of ADM in tumour tissues was upregulated notably compared with adjacent non‐tumour tissues." (PMID 40074697, 2025). "The significant upregulation of ADM in tumor tissues strengthened its potential as a biomarker for LUAD progression and its promise as a therapeutic target." (PMID 40547013, 2025). "Consistent with the known roles of adrenomedullin in tumor progression, our findings reinforced the notion that ADM functions not only as a pro-angiogenic and pro-survival factor but also as a key modulator of the TME." (PMID 40547013, 2025). "Our results revealed a significant upregulation of ADM expression in tumor tissues after resistance to EGFR-TKI treatment." (PMID 40529377, 2025). "Adrenomedullin (ADM) plays a pivotal role in the polarization of macrophages toward the M2 phenotype in cancers, which contributes to tumor progression." (PMID 40330466, 2025). "Primarily, characteristics of the tumor microenvironment, including hypoxia and nutrient deprivation, modulate ADM expression by activating pathways such as HIFs." (PMID 40565016, 2025). "In fact, pharmacological perturbation of ADM stabilises endothelial junctions in tumour vasculature but exhibits minimal effects on blood vessels in the normal brain, indicating that ADM is a selective and druggable target." (PMID 40074697, 2025). "Inhibition of ADM has been shown to suppress tumor growth, underscoring ADM’s critical involvement in sunitinib resistance." (PMID 40565016, 2025). "In experimental GBM models, inhibition of adrenomedullin (ADM) normalized tumor vasculature, enhanced drug delivery, and showed therapeutic promise." (PMID 40076738, 2025). "In the context of cancer therapy, anti-ADM antibodies offer a novel approach to combating tumor growth and angiogenesis." (PMID 39200990, 2024). "ADM, a potent vasodilator peptide consisting of 52 amino acids, has been observed to be expressed in various human tumor cell lines including those of the lung, breast, brain, prostate, and colon." (PMID 38332637, 2024). "We also explored the glycolysis‐related gene ADM and ingenol mebutate to provide a theoretical framework for anti‐tumor strategy targeting glycolysis." (PMID 38332637, 2024). "We further explored the glycolysis‐related gene ADM and IM to provide a theoretical framework for anti‐tumor strategy targeting glycolysis." (PMID 38332637, 2024). "We also explored the glycolysis‐related genes ADM and IM to develop a theoretical framework for anti‐tumor strategies targeting glycolysis." (PMID 38332637, 2024). "The DAB2+ and SPP1+ tumor-associated macrophages (TAMs) reinforce the function of FAP+ CAFs through signals such as TGF-β, PDGF, and ADM." (PMID 39239526, 2024). "For example, adrenomedullin (AM) is released from choroid plexus carcinoma; AM released from tumor cells drives both tumor and lymph node lymphangiogenesis, and AM gene dosage has been related to both mechanisms." (PMID 36980580, 2023). "In summary, our data demonstrate that adrenomedullin is an essential regulator of tumor angiogenesis which, by acting through its Gs-coupled receptor on endothelial cells, promotes endothelial cell proliferation." (PMID 36374225, 2023). "Based on co-culture experiments in vitro as well as on in vivo experiments, we show that tumor cell–derived adrenomedullin exerts a pro-angiogenic effect on endothelial cells, which is mediated by the Gs-coupled adrenomedullin receptor." (PMID 36374225, 2023).
tumor (continued). "Multiple tumors have been shown to express adrenomedullin, and it is believed to function as a potent autocrine or paracrine factor that promotes tumor cell survival and lymphangiogenesis." (PMID 36374225, 2023). "Together, these results indicate that tumor cell derived adrenomedullin promotes tumor growth through the endothelial CALCRL/Gs signaling pathway." (PMID 36374225, 2023). "Disinhibition of endothelial CCL2 results in reduced tumor progression through inhibition of adrenomedullin formation by tumor cells." (PMID 36374225, 2023). "Adrenomedullin (AM) expression induced by mast cells facilitates recruitment of endothelial cells to the tumor microenvironment, where they promote angiogenesis via secretion of VEGF, FGF-2, tryptase, and MMPa." (PMID 37370399, 2023). "We report that tumor cell–derived adrenomedullin has a pro-angiogenic as well as a direct tumor-promoting effect, and that endothelium-derived CC chemokine ligand 2 (CCL2) suppresses adrenomedullin-induced tumor cell proliferation." (PMID 36374225, 2023). "The authors identify a tumor-suppressing angiocrine function of CCL2 which is inhibited by tumor-derived adrenomedullin acting via its receptor on endothelial cells." (PMID 36374225, 2023). "In contrast, suppression of adrenomedullin expression in tumor cells led to a strong reduction in the proliferation of HUVECs and of co-cultured tumor cells." (PMID 36374225, 2023). "This strongly indicates that Gs-mediated signaling in endothelial cells regulates the formation and/or release of adrenomedullin from tumor cells through a diffusible factor." (PMID 36374225, 2023). "This confirms the role of adrenomedullin as a pro-angiogenic factor which also directly promotes tumor growth." (PMID 36374225, 2023). "Adrenomedullin is expressed both in endothelial cells and tumor cells and can induce the proliferation of both endothelial cells and tumor cells in a CALCRL- and Gαs-dependent manner." (PMID 36374225, 2023). "The staining intensity of these two genes (HMOX1, ADM) in tumor cells is higher than in normal pneumocytes." (PMID 35957802, 2022). "M2 macrophages also direct tumor progression via the secretion of adrenomedullin and (VEGF) to promote angiogenesis and expression of PD-L1 to allow immune escape of tumor cells." (PMID 35345849, 2022). "Previous studies have found that ADM is expressed in a variety of tumor tissues and cells, and can regulate tumor cell proliferation, invasion, and metastasis, and tumor angiogenesis." (PMID 36117156, 2022). "Differential analysis showed that GNAI3, PCDH7, PSEN1 and TNFSF9 were highly expressed in tumor tissues, while ADM, CD69, SLC11A2 and TLR2 were opposite." (PMID 36117156, 2022). "Tumor-derived adrenomedullin activates mast cell degranulation, leading to the release of IL-17a to promote tumor progression." (PMID 35311157, 2022). "Accordingly, genetic or pharmacologic inhibition of CGRP or ADM signaling reduced tumor-related properties in vitro and in animal models." (PMID 34029637, 2021). "Adrenomedullin –onwards AM– is a regulatory peptide whose involvement in tumor progression and metastasis has become more evident in recent years." (PMID 33489885, 2020). "Earlierstudies have shown that ADM plays critical roles in the regulation of cardiovasculardevelopment, vasotone, endothelial barrier integrity, and tumor angiogenesis." (PMID 31150417, 2019). "On the other hand, because blockage of ADMsignaling suppresses tumor xenograft growth and metastasis in animals, ADM antagonists are being developed asanti-tumor/angiogenesis therapy." (PMID 31150417, 2019). "Next, we found that ADM in tumor tissues was significantly increased when compared to that in non-tumor tissues, and that a positive correlation between mast cell degranulation and ADM production most likely derived from EpCam+ tumor cells within GC tumors." (PMID 30305610, 2018).
tumor (continued). "To evaluate the potential role of GC tumor-derived ADM in the degranulation of mast cells which expressed RAMP2 (specific subunit of ADM receptor 1 heterodimer) within tumors, we added ADMR antagonist AMA into TTCS/mast cell co-culture system." (PMID 30305610, 2018). "Recent studies has shown that elevated ADM expression in cancer cells can augment angiogenesis, reduce apoptosis, and even promote tumor proliferation." (PMID 30305610, 2018). "Several animal studies have demonstrated that inhibition of adrenomedullin leads to a reduction in tumor growth and size." (PMID 28620317, 2017). "Using clinical specimens and immunohistochemistry, we found that the expression levels of adrenomedullin and its receptors are inordinately elevated as compared to the adjacent non-tumor gastric tissues." (PMID 29179449, 2017). "NDRG1, a tumor suppressor and metastasis blocker, and ADM, which has been reported to have anti-migratory effects, were also significantly upregulated with BIX-01294." (PMID 29145444, 2017). "Though at present we can't define that myelomonocytic cells are the most important driving force of tumor growth, it provides us a new insight that myelomonocytic cell recruitment is a novel function of ADM contributing to PDAC growth." (PMID 27391260, 2016). "ADM is expressed in a variety of malignant tumor tissues, exhibits pro-mitogenic and pro-angiogenic effects, and is essential for the tumor growth in vivo." (PMID 27556517, 2016). "And adrenomedullin expression was increased in sunitinib-resistant tumor xenografts, accompanied by upregulation of phospho-ERK levels." (PMID 27556517, 2016). "ADM knockdown in tumor-bearing mice or administration of AMA, an ADM antagonist, significantly inhibited the recruitment of myelomonocytic cells and tumor angiogenesis." (PMID 27391260, 2016). "Although recruitment of myelomonocytic cells was blocked, SW1990-ADM tumors still secreted ADM to enhance neovascularization and promote tumor growth." (PMID 27391260, 2016). "Previous IHC analysis showed that HCC samples with intra-hepatic metastasis expressed strong ADM immunoreactivity in the cytoplasm of tumor cells." (PMID 26043778, 2015). "ADM mRNA expression was significantly higher in the ICC tumor tissues compared with that in the peritumoral and healthy liver tissues, according to RT-PCR." (PMID 26043778, 2015). "ADM protein was highly expressed in ICCs according to IHC, while ADM mRNA expression levels were higher in the tumor tissues compared with that in the peritumoral and healthy tissues." (PMID 26043778, 2015). "Small-molecule antagonists can effectively block bone-mediated responses to tumor-secreted adrenomedullin, and such agents warrant development for testing in vivo." (PMID 25439669, 2014). "The level of ADM expression in tumors correlates with vascular density in patients and ADM-heterozygous knockout mice have reduced neovascularization in a tumor xenograft model." (PMID 23520487, 2013). "Recently, a notable paper reported that in melanomas, TAM-derived adrenomedullin is involved in angiogenesis and tumor growth." (PMID 22778768, 2012). "It was found that the adrenomedullin derived from TAMs interacts with its receptors on endothelial cells to promote tumor growth via a paracrine loop through the activation of the eNOS signaling pathway similar to the angiogenesis cytokine VEGF." (PMID 22778768, 2012). "ADM is also a hypoxia-inducible gene which plays an important role in tumor progression and angiogenesis while IGFBP3 is a pro-apoptotic gene induced by hypoxia." (PMID 21455298, 2011). "Adrenomedullin also increased capillary cell activation and neoangiogenesis in various animal models of tissue repair or tumor growth." (PMID 20942979, 2010). "These events are involved not only in pannus progression but also in tumor development, indicating a new role for adrenomedullin." (PMID 20942979, 2010).
tumor (continued). "Adrenomedullin has been shown to be involved in carcinogenesis and tumour progression by promoting tumour proliferation, angiogenesis and the inhibition of apoptosis." (PMID 16251875, 2006). "Adrenomedullin-mediated upregulation of antiapoptotic factors in hypoxia or downregulation of pro-apoptotic factors contributes to tumour cell survival." (PMID 16251875, 2006). "In the immunohistochemical analysis, we were unable to find a correlation between ADM expression and tumour grade." (PMID 14612905, 2003). "As the ADM peptide is rapidly secreted once produced in cells, it is conceivable that ADM peptide in the blood stream of tumour patients reflects the ADM secretion from the malignancies." (PMID 14612905, 2003). "The protumorigenic activity of ADM is also in accordance with recent data that have revealed a clinical significance of ADM overexpression in malignant human tumours." (PMID 14612905, 2003). "Adrenomedullin is increasingly being regarded as a significant factor in angiogenesis and tumour growth." (PMID 11875740, 2002). "Similarly, experimental research on melanoma has demonstrated both in vitro and in vivo that antibodies neutralizing ADM and its receptors substantially inhibit tumor cell proliferation, migration, and invasion, culminating in tumor regression." (PMID 40565016, 2025). "Adrenomedullin (ADM) is a powerful vasodilatory peptide commonly present in various tumours." (PMID 40074697, 2025). "Furthermore, in the study of pancreatic ductal adenocarcinoma, ADM influences macrophages and myeloid-derived suppressor cells (MDSCs) to adopt phenotypes conducive to tumor growth, characterized by the secretion of various pro-angiogenic factors." (PMID 40565016, 2025). "The expression of ADM demonstrates intricate characteristics within tumor tissues." (PMID 40565016, 2025). "In these differentiated MCs, ADM expression is further upregulated in response to hypoxic conditions, thereby establishing autocrine and paracrine interactions with the surrounding cellular microenvironment, including tumor cells." (PMID 40565016, 2025). "Moreover, our findings elucidate the interaction between tumour cells and endothelial cells mediated by the ADM/CRLR signalling pathway." (PMID 40074697, 2025). "Notably, ADM is aberrantly overexpressed in various tumor cell lines and solid tumors, where it plays a significant role in promoting tumor angiogenesis and stimulating cellular proliferation." (PMID 40565016, 2025). "The results indicated that ADM staining was stronger in tumours compared to normal tissues." (PMID 40074697, 2025). "Furthermore, the inducible deletion of pulmonary EC-specific Adrenomedullin (AM)-RAMP2 signaling results in increased permeability of tumor vessels, enhancing tumor metastasis." (PMID 40650130, 2025). "Notably, ADM expression showed strong spatial co-localization with metabolically active tumor regions, particularly those enriched in nucleotide metabolism, implying a potential role for ADM in supporting tumor metabolic reprogramming." (PMID 40547013, 2025). "Additionally, elevated ADM expression was correlated with increased tumour‐infiltrating immune cells and higher immune checkpoint expression." (PMID 40074697, 2025). "Targeting hypoxia‐TAM‐secreted adrenomedullin for tumor vessel normalization." (PMID 39297872, 2024). "In addition to its pro-angiogenic effect, adrenomedullin also inhibits endothelial formation of CCL2, which acts as an angiocrine factor and suppresses formation of adrenomedullin by tumor cells." (PMID 36374225, 2023). "To test whether CCL2 inhibits adrenomedullin formation in tumor cells, we incubated different tumor cells with CCL2." (PMID 36374225, 2023). "A predominant role of tumor cell–derived adrenomedullin was also seen under in vivo conditions." (PMID 36374225, 2023). "However, this activity can be suppressed by tumor-derived adrenomedullin and potentially also by other mediators which activate Gs-coupled receptors." (PMID 36374225, 2023).